IL6 (interleukin 6)
Diseases named in the same sentence as IL6 in open-access papers (continued):
Sharing a sentence is not in itself a finding about the gene and the disease.
Insulin resistance (continued). "IL-6 can also certainly avert insulin synthesis, and excess IL-6 leads to severe pancreatic islet cytotoxicity and cause insulin resistance." (PMID 31337059, 2019). "High levels of interleukin-6 (IL-6), an inflammatory cytokine, are associated with insulin resistance (IR) and T2D likely due to greater white adipose tissue IL-6 secretion." (PMID 30691224, 2019). "The role of IL-6 in experimental animals and associated insulin resistance remained controversial over the years." (PMID 31554278, 2019). "For instance, IL-6 has a complex role in metabolism and has been shown to increase insulin sensitivity, but has also been linked to insulin resistance." (PMID 31757005, 2019). "Further, elevated IL-6 levels are a good indicator of an inflamed state, which can play a key role in the development of insulin resistance and other associated diseases." (PMID 31024337, 2019). "IL-6, a pro-inflammatory cytokine, is released by a number of tissues, mainly adipose tissue, and it causes insulin resistance by downregulating the expression of glucose transporter-4 (GLUT-4) and IRS-1." (PMID 31597283, 2019). "This study showed intraocular IL-6 levels were associated with insulin resistance and smoking status, while intraocular VEGF levels were influenced by Lp-A." (PMID 31396410, 2019). "Adipose tissue-derived pro-inflammatory cytokines such as TNF-α and IL-6 can cause insulin resistance in adipose tissue, liver, and skeletal muscle by impairing insulin action." (PMID 31075962, 2019). "Interleukin-6 (IL-6) is upregulated in T2D, and is implicated in the development of insulin resistance." (PMID 30301129, 2018). "An association between changing IL-6 and changing DI was also largely mitigated by adjustment for changing insulin resistance." (PMID 30102726, 2018). "The association was the strongest for changing BMI and was largely explained by changing insulin resistance; the association with changing IL-6 was also largely explained by changing insulin resistance." (PMID 30102726, 2018). "Several inflammatory cytokines, such as tumor necrosis factor-α (TNF-α) and interleukin-6 (IL-6), have been implicated in the causation of insulin resistance and appear to confer an increased risk of microvascular complications in type 2 diabetes mellitus." (PMID 30526660, 2018). "Prospective studies have shown that GDM is linked to the down-regulation of anti-inflammatory cytokines (e.g., IL-4 and IL-10) and up-regulation of pro-inflammatory cytokines implicated in insulin resistance (e.g., IL-6 and TNF-α)." (PMID 30563117, 2018). "Pregnancy is also associated with a transient worsening of the cardiovascular risk profile including increases in dyslipidaemia, insulin resistance, oxidative stress, cytokines such as IL-6 and TNF-α, and inflammatory markers such as CRP." (PMID 28193219, 2017). "These pathogenic IL-6+ Th17 cells then circulate to other insulin-targeted tissues (the liver and muscle), leading to insulin resistance." (PMID 28061846, 2017). "Although low-grade inflammation, characteristic of elevated IL-6 levels, has been associated with obesity and insulin resistance, it is markedly produced and released after an acute bout of exercise." (PMID 28555043, 2017). "TNF-α and IL-6 can cause insulin resistance by suppressing expression of the insulin receptor substrate −1 (IRS-1) and GLUT-4 though activation of NF-KB pathway." (PMID 28166749, 2017). "Of the major cytokines expressed in adipose tissue from obese subjects IL-1β, IL-6, and TNFα, have been linked with the development of insulin resistance." (PMID 28957383, 2017). "STAT3, which is downstream of IL-6 signaling, is reported to be associated with IL-6-induced insulin resistance and gluconeogenesis in the liver and muscle." (PMID 28706484, 2017). "STAT3 is implicated in development of IL-6-induced insulin resistance in cultured skeletal myotubes obtained from patients with impaired glucose tolerance." (PMID 28706484, 2017).
Insulin resistance (continued). "Insulin resistance has been associated with cytokines, including interleukin-6 and tumor necrosis factor alpha soluble receptor, both of which are elevated in chronic obstructive pulmonary disease (COPD)." (PMID 28142050, 2017). "The increased expression of IL-6 in ATMs caused by LP diets will exacerbate insulin resistance in adult rats fed HE diets." (PMID 28141871, 2017). "This implies that high plasma levels of TNF-α and IL-6 seen in instances of insulin resistance is due to EPA, DHA, and AA deficiency." (PMID 28824543, 2017). "Higher levels of CRP, high sensitivity CRP (hsCRP), and IL-6 have consistently been associated with an increased risk of insulin resistance, hyperinsulinism, impaired glucose tolerance, type 2 diabetes, and metabolic syndrome." (PMID 28753646, 2017). "For example, TNFα, can cause peripheral and hepatic insulin resistance; accordingly, upregulation of TNFα and IL-6 by chronic alcohol was associated with impaired insulin-mediated glucose uptake by WAT." (PMID 28212318, 2017). "ATM1s produce large amounts of pro-inflammatory mediators such as TNF-α, IL-1β, and IL-6, which can cause insulin resistance in adipose tissue." (PMID 29141038, 2017). "M1 macrophages, which represent a pro-inflammatory state, can secrete inflammatory cytokines such as tumor necrosis factor (TNF)-α, interleukin-6 (IL-6) and IL-1β that interfere with insulin signaling, and cause adipocyte dysfunction and insulin resistance." (PMID 27878229, 2016). "IL-6 was one of the first pro-inflammatory cytokines to be implicated in insulin resistance pathogenesis and as a cardiovascular risk factor." (PMID 26862350, 2016). "IL-6 is elevated in obese subjects with insulin resistance and directly causes adipose insulin resistance." (PMID 26901838, 2016). "IL-6 is also associated with insulin resistance, fibrosis and tumorigenesis involving the activation of STAT3, Akt, Erk, JNK pathways." (PMID 27703473, 2016). "In adipose tissue, IL-6 mediates inflammatory processes and causes insulin resistance by downregulating GLUT4 and IRS-1 expression." (PMID 27069930, 2016). "Pro-inflammatory cytokines (such as tumor necrosis factor-α and interleukin-6) have been reported to be increased in depression and have also been implicated in the development of insulin resistance." (PMID 26891344, 2016). "IL-6 treatment restored insulin resistance in obese Wnt5a-deficient mice, suggesting this inflammatory cytokines in adipose tissue promote obesity-induced metabolic dysfunction." (PMID 27608847, 2016). "Insulin resistance and hyperglycemia increase the effect of cytokines on the liver and cause the secretion of IL-6 and TNF-α from monocytes and macrophage." (PMID 28050278, 2016). "Long-term treatment of adipocytes with IL-6, IL-1β, or TNFα was shown to inhibit insulin signaling and cause insulin resistance." (PMID 27066503, 2016). "Insulin resistance in pregnancy has been particularly associated with adiponectin and leptin, which are secreted only by the adipose tissue, and IL-6 and TNF-α, which are also secreted by the adipose tissue and other cells." (PMID 27651836, 2016). "Increased production of pro-inflammatory cytokines such as TNFα and IL-6 has been reported to be associated with insulin resistance." (PMID 26913058, 2016). "BPA plasma levels (ELISA), metabolic risk factors, homeostasis model assessment of insulin resistance index, plasma monocyte chemoattractant protein 1, interleukin-6 (IL-6) and tumor necrosis factor-alpha were performed." (PMID 26021871, 2015). "C-reactive protein (CRP), which is an inflammatory biomarker induced by IL-6, was increased by insulin resistance and was associated with an increased risk of endometrial cancer in postmenopausal women." (PMID 25866823, 2015).
Insulin resistance (continued). "The adipose tissue can synthesize and release pro-inflammatory cytokines, as TNF-alpha, IL-1 and IL-6, and these inflammatory markers are associated with body fat mass and involved in multiple metabolic pathways relevant to insulin resistance." (PMID 25922592, 2015). "A rise in IL-6 in pregnancy, principally due to placental production, has been linked to pregnancy related insulin resistance." (PMID 26110385, 2015). "Recent several studies have demonstrated that over-nutrition and insulin resistance increase the production of proinflammatory cytokines such as IL1β and IL6, which causes pancreatic β-cell dysfunction." (PMID 25915406, 2015). "Higher intramuscular adipose tissuewas strongly associated with insulin resistance and higher serum inflammatory markers including C-reactive protein, interleukin-6, and tumor necrosis factor-alpha." (PMID 26030144, 2015). "Prospective studies have shown that GDM is linked to the down-regulation of adiponectin and anti-inflammatory cytokines (e.g., IL-4 and IL-10) and up-regulation of leptin and pro-inflammatory cytokines implicated in insulin resistance (e.g., IL-6 and TNF-α)." (PMID 26110385, 2015). "Inflammatory mediators such as TNFα and IL-6 are highly associated with the development of insulin resistance in the setting of obesity." (PMID 26090470, 2015). "Another pro-inflammatory cytokine, IL-6, is considered to cause insulin resistance in skeletal muscles and liver due to defects in phosphorylation of insulin receptor substrate, causing a decrease in gluconeogenesis and an increase in glycogenolysis." (PMID 24481132, 2014). "For instance, IL-6 inhibits insulin receptor substrate 1, impairs insulin stimulated glucose transport, and causes insulin resistance." (PMID 25195639, 2014). "TNF-α and IL-6 are proinflammatory cytokines associated with an increased insulin resistance, inhibition of insulin receptor autophosphorylation, and signal transduction." (PMID 24741576, 2014). "The evidence suggests an association between chronic elevations of IL-6 and hepatic insulin resistance." (PMID 24733551, 2014). "Proinflammatory M1 macrophages induce an inflammatory state and insulin resistance through inhibition of insulin signaling caused by IL-6 and TNF-alpha." (PMID 24741627, 2014). "After 4 weeks on HFD, the phosphorylation and abundance of signaling proteins associated with insulin resistance, physical activity, and IL‐6 were determined in soleus muscle, gastrocnemius/plantaris muscles, and liver tissue." (PMID 24997069, 2014). "Chronically elevated IL‐6 mediates inhibitory effects on insulin signaling and glucose metabolism, and therefore, has been linked to insulin resistance in peripheral tissues." (PMID 24997069, 2014). "Inflammatory mediators such as tumor necrosis factor alpha (TNFα) and interleukin-6 (IL-6) are important mediators of catabolic responses such as protein loss and of metabolic disturbances such as insulin resistance." (PMID 25614714, 2014). "The role of 4-HNE and IL-6 as key players in modifying the association between sustained hypoxia and insulin resistance merits further investigation." (PMID 24733551, 2014). "In contrast, visceral adipose tissue is positively associated with risk of insulin resistance and shows higher monocytes infiltration and IL-6 production than subcutaneous adipose tissue to induce inflammation in obese subjects." (PMID 23781214, 2013). "TNFα regulates IL-6 synthesis and aromatase expression in the adipose tissue, and it has been implicated in the development of insulin resistance, all potential promoters of breast tumorigenesis." (PMID 23819063, 2013). "Accordingly, HFD fed SFRP5 deficient mice Sfrp−/− have insulin resistance and fatty liver along with enhanced inflammatory macrophage accumulation to produce IL-6, TNF-α, and CCL2 suggesting that SFRP5 is an anti-inflammatory adipokine." (PMID 23781214, 2013).
Insulin resistance (continued). "The inflammatory regulator IL-6 has also emerged as a factor that is implicated in hepatic insulin resistance." (PMID 23762871, 2013). "TNF-α actively participates in the development of insulin resistance and IL-6 is linked with type II diabetes." (PMID 24302970, 2013). "The “classic” adipocytokines such as adiponectin, TNF-α, and IL-6 have been regarded as consistent surrogate markers to reflect cardiovascular risk and other metabolic abnormalities in subjects with insulin resistance." (PMID 23970879, 2013). "Previously, it was shown that chronic exposure to TNF-α decreased insulin receptor phosphorylation in adipocytes and that increased levels of TNF-α, IL-6 and IL-1β are linked to systemic inflammation and accompany insulin resistance." (PMID 23915208, 2013). "In this regard, higher levels of TNFα and IL-6 have been associated with excess adiposity levels and insulin resistance." (PMID 22768323, 2012). "The present work also verified that aside from C4, TNF-α, and IL-6, inflammatory markers were associated with waist circumference and insulin resistance, emphasizing that this syndrome is proinflammatory." (PMID 21822486, 2012). "Along with MCP-1 and F4/80, we observed higher expression levels of proinflammatory cytokines, such as IL-1β, IL-6 and TNFα, which are actively secreted by macrophages or adipocytes and cause insulin resistance." (PMID 22272317, 2012). "The association of IL-6 with insulin resistance was suggested by the observation in animal studies that passive immunoneutralisation of IL-6 led to an improved insulin sensitivity in insulin resistant mice with transgenic NFκB activation." (PMID 22615828, 2012). "Inflammatory markers including interleukin-6 (IL-6) have also been implicated in the development of insulin resistance." (PMID 21914162, 2011). "The insulin resistance in obese mice was associated with the increased expression of inflammatory markers Cd68, Il-6 and Il-1α; in contrast, most of these genes were down-regulated in CR mice." (PMID 20307313, 2010). "Of the many interleukins identified, IL-6 exhibits a strong association with insulin resistance in human subjects." (PMID 21179199, 2010). "Diabetes in conjunction with LF had decreased levels of TNF-α and IL-6 (cytokines that have already been associated with insulin resistance (IR)), compared to those with DM alone." (PMID 20559443, 2010). "Substantial experimental evidence and cross-sectional data suggest that IL-6 is associated with hyperglycemia, insulin resistance, and overt type 2 diabetes." (PMID 21122092, 2010). "The glycolipid β-galactosylceramide-3-O-sulfate (sulfatide) modulates cytokine expression, including TNF-α and Interleukin 6 (IL-6) which are known to cause insulin resistance." (PMID 19587831, 2009). "Not only has IL-6 been linked to insulin resistance but also IL-6 level is increased in serum of patients with NASH, NAFLD or alcoholic hepatitis." (PMID 19936233, 2009). "Afteradjustment for multiple confounders, including IL-6, high plasma TNFconcentrations are associated with insulin resistance." (PMID 19148295, 2008). "Inflammation caused by cardiac surgery increased insulin resistance in a time dependent manner which was paralleled by an induction of cortisol, TNFα, IL6, resistin and leptin while adiponectin serum levels were decreased." (PMID 19087258, 2008). "The IL-6 -174G > C common functional gene variant has consistently been associated with increased plasma IL-6, insulin resistance, and increased cardiovascular risk." (PMID 17374166, 2007). "In summary, low circulating concentrations of leptin, increased fat oxidation and insulin resistance are associated with increased circulating concentrations of cortisol and interleukin-6 in weight-losing patients with pancreatic cancer." (PMID 15026790, 2004).
Insulin resistance (continued). "Specifically in cardiometabolic settings, chronically elevated IL-6 has been associated with central adiposity, insulin resistance, endothelial dysfunction, and increased cardiovascular risk, reflecting sustained activation of adipose and vascular compartments." (PMID 41602164, 2026). "In addition, VAT also releases pro‐inflammatory cytokines such as tumour necrosis factor‐alpha (TNF‐α) and interleukin‐6 (IL‐6), both of which are implicated in insulin resistance and endothelial dysfunction." (PMID 41251158, 2026). "Excess adipose tissue, particularly visceral fat, is metabolically active and acts as a source of pro-inflammatory adipokines, such as tumor necrosis factor-alpha (TNF-α) and interleukin-6 (IL-6), which are associated with systemic insulin resistance and endothelial dysfunction." (PMID 41301434, 2025). "Insulin resistance, a hallmark of prediabetes, contributes to chronic low-grade inflammation and endothelial dysfunction, which can in turn influence levels of circulating biomarkers such as IL-6, D-dimer, and S100B." (PMID 41150802, 2025). "IL-6 levels were strongly associated with hypertriglyceridemia (OR = 1.096, 95% CI: 1.044–1.151, p < 0.001) and insulin resistance (OR = 1.068, 95% CI: 1.030–1.107, p < 0.001), while TNF-α correlated with abdominal obesity (WHtR OR = 1.429, 95% CI: 1.005–2.031, p = 0.047)." (PMID 40137151, 2025). "IL-6 and IL-8 are key mediators linking adipose inflammation to metabolic dysfunction, and both have been implicated in impairing adipogenesis and promoting insulin resistance." (PMID 41574186, 2025). "A separate study evaluating the role of SNPs in interleukin 6 (IL-6) in Mexican Americans from South Texas identified the rs1800796 variant to be correlated with insulin resistance, larger waist circumference, increased high-sensitive C-reactive protein, and reduced IL-6 levels." (PMID 40745234, 2025). "IL-6 is a pro-inflammatory cytokine released mainly by the immune cells, the adipocytes, and the endothelial cells, whose increased levels have been consistently linked to insulin-resistance and type 2 diabetes." (PMID 40283592, 2025). "High levels of chronic systemic IL-6 cause insulin resistance and general metabolic dysfunction." (PMID 40122610, 2025). "Visceral fat accumulation in PLHIV is linked to CD8+ T cell activation, insulin resistance, and higher levels of IL-6 and TNF-α, indicating that central obesity may play an important role in immune-metabolic interactions." (PMID 41305316, 2025). "It is reported that the cytokines IL-6 and IL-1β collectively can cause insulin resistance." (PMID 41012578, 2025). "TNF-α and IL-6 may cause insulin resistance by suppressing the expression of GLUT-4 and insulin receptor substrate-1 (IRS-1) and activating the NF-κβ pathway." (PMID 40541974, 2025). "Additionally, it inhibits nuclear factor-kappa B (NF-κB) signaling, leading to reduced expression of pro-inflammatory cytokines such as TNF-α and IL-6, which are implicated in insulin resistance." (PMID 40565030, 2025). "Taken together with our findings, the presence of detectable HIV-RNA under ART may be associated with increased accumulation of visceral fat, insulin resistance, and IL-6 and decreased mRNA expression of LPL in adipose tissue." (PMID 41156460, 2025). "IL-6 appears to be more specifically linked to lipid abnormalities and insulin resistance." (PMID 40137151, 2025). "Taken together, the association with WHR (abdominal fat), insulin resistance and IL6/CRP might indicate a potential role of BA in inducing and/or maintaining the so-called metabolic inflammation often observed in prediabetes and type 2 diabetes patients." (PMID 40045464, 2025). "To clarify the causality relationship between cytokines IL-1α, IL-1β and IL-6 from macrophages and insulin resistance, we co-cultured primary hepatocytes with BMDMs and treated them with different combinations of insulin, TSH, IL-1 blocker IL-1RA or IL-6 blocker IL-6ST." (PMID 40523992, 2025).